TRPA1 (transient receptor potential cation channel subfamily A member 1)
Diseases named in the same sentence as TRPA1 in open-access papers (continued):
Sharing a sentence is not in itself a finding about the gene and the disease.
pulmonary fibrosis (5 papers, 2019 to 2025). Chronic progressive interstitial lung disorder characterized by the replacement of the lung tissue by connective tissue, leading to progressive dyspnea, respiratory failure, or right heart failure. "Given the role of TRPA1 in fibrosis, its deficiency or inhibition could have therapeutic effects on diseases such as pulmonary fibrosis." (PMID 38635081, 2024). "Therefore, TRPA1 inhibition can effectively alleviate the mechanical alterations associated with pulmonary fibrosis." (PMID 38635081, 2024). "Intriguingly, a recent study of idiopathic pulmonary fibrosis has demonstrated a role for TRPA1 in both fibrotic modulation and M2 macrophage polarisation control." (PMID 40640495, 2025). "Western blot and immunohistochemical analyses showed decreased fibrosis markers and partial recovery of cellular integrity, underscoring TRPA1's potential as a target for mitigating lung fibrosis." (PMID 38635081, 2024). "Recently, TRPA1 activation induced macrophage polarization to the M2 phenotype, and we further explored its role in pulmonary fibrosis." (PMID 38635081, 2024). "Our research marks the first to show a marked activation of TRPA1 in a bleomycin-induced mouse model of pulmonary fibrosis." (PMID 38635081, 2024). "To reveal the complex role of TRPA1 in pulmonary fibrosis and macrophage differentiation, we carefully designed in vivo and in vitro experiments to capture models at different time points and dissect their pathological changes." (PMID 38635081, 2024). "Overall, targeting TRPA1 channels presents promising therapeutic potential in managing pulmonary fibrosis by reducing pro-fibrotic marker expression, inhibiting M2 macrophage polarization, and diminishing collagen deposition." (PMID 38635081, 2024). "Acknowledging these shortcomings, we plan to develop TRPA1 knockout mouse models and observe the effects at various time points to gain a more comprehensive understanding of the temporal dynamics of TRPA1 involvement in pulmonary fibrosis." (PMID 38635081, 2024). "Our study demonstrated that inhibiting TRPA1 dampened the shift towards M2 macrophage polarization in a mouse model of pulmonary fibrosis, primarily by blocking the TGF-β1-Smad2 pathway's phosphorylation process." (PMID 38635081, 2024). "In our study, TRPA1 inhibition reduced macrophage polarization towards the M2 phenotype in a mouse model of pulmonary fibrosis." (PMID 38635081, 2024). "We have previously also shown that the expression of TRPV1 and TRPA1 increased in the lungs of guinea pigs with bleomycin-induced pulmonary fibrosis." (PMID 34078339, 2021). "Our previous study also showed that expression of TRPV1/TRPA1 was upregulated in a guinea pig model of bleomycin-induced pulmonary fibrosis with chronic cough." (PMID 34078339, 2021). "Expression of TRPV1/TRPA1 was upregulated in the chronic cough related to bleomycin induced pulmonary fibrosis in guinea pigs, which provided new insights into the mechanism of IPF-associated cough hypersensitivity." (PMID 30717786, 2019). "Furthermore, in discussing the paradoxical role of TRPA1 in lung fibrosis and its complex relationship with TGF-β1, the literature presents intriguing insights." (PMID 38635081, 2024). "This study demonstrated that inhibiting TRPA1 channels can decrease pulmonary fibrosis in mice." (PMID 38635081, 2024). "The involvement of TRPA1 in pulmonary fibrosis has garnered significant interest." (PMID 38635081, 2024). "Herein, we hypothesized that the cough reflex increases in a model of bleomycin-induced pulmonary fibrosis in guinea pigs, which is associated with up-expression of TRPV1 and TRPA1." (PMID 30717786, 2019). "Using a bleomycin-induced pulmonary fibrosis model in C57BL/6J mice, we assessed the therapeutic potential of the TRPA1 inhibitor HC-030031." (PMID 38635081, 2024).
pulmonary fibrosis (continued). "Immunofluorescence and Western blot analyses confirmed these findings, underscoring TRPA1 inhibition's potential to mitigate M2 polarization and interfere with the TGF-β1-Smad2 pathway, offering a promising direction for pulmonary fibrosis treatment." (PMID 38635081, 2024). "We have previously shown that expression of TRPA1 and TRPV1 in the lungs of a guinea pig model of bleomycin-induced pulmonary fibrosis was elevated, which was companied with increased cough sensitivity." (PMID 34078339, 2021). "In summary, the regulation of TRPA1 channels by TGF-β1 suggests that TRPA1 may play a key role in macrophage polarization, which can affect the balance between the M1 and M2 phenotypes and influence the progression of pulmonary fibrosis." (PMID 38635081, 2024). "To further address these unknown issues, we aimed to explore the expression of TRPA1 and TRPV1 in the jugular ganglia and nodose ganglia and that of neurogenic indicators such as SP, CGRP, and NK1R in the lungs using an established guinea pig cough model of pulmonary fibrosis induced with bleomycin." (PMID 34078339, 2021).
acute pancreatitis (4 papers, 2016 to 2021). An acute inflammatory process that leads to necrosis of the pancreatic parenchyma. "Early intervention with TRPV1 and TRPA1 antagonists (within three weeks of the development of acute pancreatitis) attenuated the transition to and development of CP and downstream pain behaviors in mice." (PMID 34829924, 2021). "Another study highlighted the synergistic role of TRPV1 and TRPA1 in acute pancreatitis development." (PMID 34829924, 2021). "The pancreatitis-associated pain was shown to be related to TRPA1 and TRPV1 expression, and it functioned in afferents in an experimental acute pancreatitis model in mouse." (PMID 30087301, 2018). "Furthermore, our novel dual-channel blocker inhibited inflammation and pain-associated behavior in a model of acute pancreatitis – known to also rely on TRPV4 and TRPA1." (PMID 27247148, 2016). "Therefore, targeting of TRPA1 and TRPV1 in patients with recurrent bouts of acute pancreatitis may inhibit the progression to chronic pancreatitis." (PMID 30087301, 2018).
Cerebral ischemia (4 papers, 2021 to 2025). Restriction of arterial blood supply to the brain associated with insufficient oxygenation to support the metabolic requirements of the tissue. "As an example, in an experimental model of cerebral ischemia, endothelial cell-specific TRPA1 null rodents exhibited larger infarcts, indicating that endogenous agonist activation of TRPA1 led to protective effects." (PMID 38333756, 2024). "Under this hypothesis, TRPA1 stimulation has recently been proposed as an alternative approach to rescue CBF in several brain disorders, including brain ischemia." (PMID 39949092, 2025).
channelopathies (4 papers, 2017 to 2023). "The gain of function of p.Ala172Val in TRPA1 in response to agonists extends our knowledge of painful TRPA1 channelopathies." (PMID 36895957, 2023). "This introduces LUAD as a potential TRPA1-modulated channelopathy, with TRPA1 and FGFR2 acting as valuable cancer biomarkers." (PMID 29038531, 2017).
chronic pancreatitis (4 papers, 2013 to 2023). A chronic inflammatory process causing damage and fibrosis of the pancreatic parenchyma. "In the pancreas, TRPA1 was shown to contribute to pain and inflammation in a mouse model of chronic pancreatitis induced by trinitrobenzene sulfonic acid." (PMID 38188196, 2023). "In a different area of research, it was demonstrated that TRPA1 antagonism can prevent the transition from acute to chronic inflammation and pain in a model of chronic pancreatitis by reducing neurogenic inflammation." (PMID 36430567, 2022). "TRPA1 channels are involved in the development of acute and chronic pancreatitis." (PMID 27903970, 2017).
epilepsy (4 papers, 2014 to 2025). A brain disorder characterized by episodes of abnormally increased neuronal discharge resulting in transient episodes of sensory or motor neurological dysfunction, or psychic dysfunction. "Our previous study indicated that auricular electroacupuncture can attenuate epilepsy by altering the TRPA1, pPKCα, pPKCε, and pERk1/2 signaling pathways in KA-induced epilepsy in rats." (PMID 28386293, 2017). "Additionally, upregulated TRPA1 expression is observed in the hippocampus of kainic acid– (KA‐) induced rat epilepsy model, and EA treatment reverses hippocampal neurons overexcitation by reducing TRPA1 and pERK1/2 (an inflammatory mediator) levels." (PMID 41399206, 2025). "The results indicated that TRPA1, but not TRPV4, protein levels increased in the KA-induced epilepsy model." (PMID 25147437, 2014).
irritable bowel syndrome (4 papers, 2016 to 2025). Irritable bowel syndrome (IBS) is a chronic functional condition of the lower gastrointestinal (GI) tract characterized by abdominal pain or discomfort and disordered bowel habit (diarrhea, constipation, or fluctuation between the two). "This can lead to an increased responsiveness of TRPA1 in the gut, contributing to abdominal pain and hypersensitivity in conditions such as irritable bowel syndrome (IBS)." (PMID 39022308, 2024).
myocardial ischemia (4 papers, 2019 to 2024). A disorder of cardiac function caused by insufficient blood flow to the muscle tissue of the heart. "A study showed that TRPA1 gene-knockout myocardial ischemia–reperfusion mice alleviated myocardial injury, indicating that TRPA1 channel activation mediates myocardial ischemia–reperfusion injury." (PMID 32903613, 2020). "The role of TRPA1 may vary from different animal models and may be distinct at different stages of myocardial ischemia and MI." (PMID 39323758, 2024). "In addition to neurons, TRPA1 has also been shown to contribute to cardiac tissue damage following myocardial ischemia-reperfusion injury, and bone cell apoptosis in rat chondrocytes." (PMID 33910636, 2021). "This may be related to the accumulation of free radicals and unsaturated aldehydes generated after myocardial ischemia and reperfusion to activate TRPA1 channel." (PMID 32903613, 2020). "Therefore, TRPA1 could be a potential drug target for reducing myocardial ischemia–reperfusion injury." (PMID 32903613, 2020).
nasopharyngeal carcinoma (4 papers, 2021 to 2024). A carcinoma arising from the nasopharyngeal epithelium. "TRPA1 expression in cancer is controversial, with gene over-expression linked to poor survival in nasopharyngeal carcinoma and gene under-expression linked to poor survival in renal clear cell carcinoma." (PMID 34090518, 2021). "The up-regulation of TRPA1 protein is associated with the progression of nasopharyngeal carcinoma." (PMID 39759147, 2024). "TRPA1 upregulation was detected by immunohistochemistry in nasopharyngeal carcinoma patients, which was negatively predictive for disease-specific, distal metastasis- and local recurrence-free survivals." (PMID 35163843, 2022). "Although several papers are available on TRPV1 expression in the oral mucosa under normal and pathological conditions, there is only one paper about TRPA1 immunopositivity in nasopharyngeal carcinoma." (PMID 35163843, 2022). "TRPA1 expression is markedly enhanced in nasopharyngeal carcinoma and OSCC." (PMID 39759147, 2024).
oropharyngeal dysphagia (4 papers, 2020 to 2026). "The stimulation of swallowing-related regions with a dual TRPV1 and TRPA1 agonist, piperine, has been observed to improve swallowing function in patients with oropharyngeal dysphagia." (PMID 32867366, 2020). "Previous studies have found that capsaicinoids (TRPV1 agonists) and piperine (TRPA1 and TRPV1 agonists) improve the swallowing response in patients with oropharyngeal dysphagia." (PMID 41548911, 2026). "Oropharyngeal TRPA1 and TRPV1 receptors appear to be promising therapeutic targets for the development of active treatments for patients with oropharyngeal dysphagia." (PMID 41548911, 2026). "In conclusion, our systematic review found that TRPV1, TRPA1 and TRPM8 agonists have beneficial effects for patients with neurogenic oropharyngeal dysphagia when compared to placebo interventions." (PMID 34337829, 2022). "Furthermore, in clinical studies, TRPV1, TRPA1, and TRPM8 agonists improved the efficacy, safety, and physiology of swallowing in patients with oropharyngeal dysphagia." (PMID 36909278, 2023).
pancreatic ductal adenocarcinoma (4 papers, 2021 to 2026). An infiltrating adenocarcinoma that arises from the epithelial cells of the pancreas. "TRPA1 was also detected in human pancreatic ductal adenocarcinoma cells (PDACs), which displayed higher levels of TRPA1 mRNA expression as compared to non-neoplastic cells." (PMID 37174661, 2023). "To date, no reports have addressed the expression and function of TRPA1 in pancreatic ductal adenocarcinoma (PDAC) cells." (PMID 33479347, 2021).
small cell lung carcinoma (4 papers, 2017 to 2022). Small cell lung cancer (SCLC) is a highly aggressive malignant neoplasm, accounting for 10-15% of lung cancer cases, characterized byrapid growth, and early metastasis. "TRPA1 is both overexpressed in small cell lung cancer (SCLC) and plays a role in cell survival since it is able to prevent apoptosis." (PMID 36139480, 2022). "Small cell lung cancer cell lines were found to functionally express TRPA1 and activation of TRPA1 prevented apoptosis and led to increased cell survival, suggesting a potential role in tumour progression and a disease-modifying effect of chronic TRPA1 inhibition." (PMID 31547502, 2019). "Stimulation of TRPA1 by allyl isothiocyanate (AITC), at 10 mM, promotes cell survival of small cell lung cancer cells (SCLCs)." (PMID 31801263, 2019). "It has been demonstrated that TRPA1 activation led to calcium- and Src-dependent stimulation of ERK1/2 in human small cell lung cancer cells." (PMID 28220825, 2017).
type II diabetes (4 papers, 2018 to 2024). "The activity of AMPK is impaired during the early stage of hyperglycemia in db/db mouse models of type 2 diabetes and is associated with a concomitant increase in membrane TRPA1 and mechanical allodynia." (PMID 34440581, 2021). "Consequently, the definite contribution of TRPA1 to glibenclamide-associated effects in type II diabetes patients remains to be clarified." (PMID 30087301, 2018). "Since TRPA1 is ubiquitinated through the Nedd4-2 pathway, abnormal Nedd4-2 distribution causes TRPA1 membrane accumulation in DRG neurons and produces mechanical allodynia in db/db mice with type 2 diabetes." (PMID 34440581, 2021). "Besides TRPA1, TRPM5 is also often associated with type II diabetes." (PMID 30087301, 2018).
viral infection (4 papers, 2017 to 2025). "One could expect relatively greater TRPA1 function and therefore a more pronounced response to TRPA1 antagonists in Th1-type conditions, such as in viral infection and perhaps non-Th2 asthma." (PMID 37386145, 2023). "TRPA1 and TRPV1 have been implicated in the cough reflex sensitization, and they are expressed on afferent sensory airway nerves and airway epithelial cells and are activated by inhaled irritants such as OVA and virus infection." (PMID 34099759, 2021). "In this study we examined whether virus infection by these viruses in bronchial epithelial cells or neuronal cells up-regulates TRPV1, TRPA1 and ASICS3 expression." (PMID 28187208, 2017).
cerebral infarcts (3 papers, 2018 to 2023). "Loss of TRPA1 signaling in endothelial cells of cerebral arteries increased cerebral infarcts following permanent middle cerebral artery occlusion in mice." (PMID 30239332, 2018).
childhood asthma (3 papers, 2017 to 2022). "TRPA1 is also thought to be a key channel involved in the late asthmatic response in a rat model of allergic inflammation, and TRPA1 gene polymorphisms have been associated with childhood asthma." (PMID 28532657, 2018). "Experiments using Trpa1−/− mice and TRPA1 antagonists revealed a critical role in allergic and non-allergic airway inflammation as well as hyper-reactivity, and genetic studies in humans suggested that TRPA1 may play a role in the development of childhood asthma." (PMID 35053420, 2022).
clear cell renal cell carcinoma (3 papers, 2017 to 2024). "This analysis revealed that TRPA1 overexpression is related to overall survival only in renal clear cell carcinoma (KIRC)." (PMID 39770499, 2024). "So, in clear renal cell carcinoma, the only cancer type with high expression of TRPA1 correlated with better patient survival, it is important to know the stage of the tumour and the degree of infiltration so that TRPA1 can eventually be used as a target in therapy." (PMID 39770499, 2024).
Cognitive impairment (3 papers, 2023 to 2024). Abnormal cognition is characterized by deficits in thinking, reasoning, or remembering. "(iv) BCAS-induced cognitive impairment and white matter injury were accelerated by astrocyte-specific, but not by endothelial cell– or oligodendrocyte lineage cell–specific, TRPA1 deficiency." (PMID 37478173, 2023). "With this, we showed that only astrocyte-specific, but not endothelial cell– or oligodendrocyte lineage cell–specific, TRPA1-deficient mice exhibited aggravated cognitive impairment and white matter injury during early-stage CCH." (PMID 37478173, 2023). "The findings of this study are as follows: (i) TRPA1 deficiency accelerated BCAS-induced cognitive impairment and white matter injury during early-stage CCH (on day 14)." (PMID 37478173, 2023). "Our findings provide preliminary evidence suggesting a mechanism linking olfactory and cognitive function, highlighting the potential significance of TRPA1 as a biomarker for cognitive impairment." (PMID 38915349, 2024). "We show that TRPA1 deficiency accelerates BCAS-induced cognitive impairment and white matter injury and that the increase of leukemia inhibitory factor (LIF) through TRPA1 stimulation in astrocytes plays a protective role in CCH-induced VCI." (PMID 37478173, 2023). "Next, we assessed cognitive impairment and white matter damage on postoperative days 14 and 28 in wild-type (WT) and TRPA1-KO mice." (PMID 37478173, 2023). "H2S/H2Sn, 3MST, and TRPA1 channels have therapeutic potential for psychiatric diseases and cognitive deficits." (PMID 37907526, 2023). "In conclusion, TRPA1 plays a protective role in CCH-induced cognitive impairment and white matter injury by activating astrocytes, increasing LIF production, and promoting OPC myelination." (PMID 37478173, 2023). "(ii) TRPA1 stimulation with cinnamaldehyde on days 15 to 24 ameliorated BCAS-induced cognitive impairment and white matter injury." (PMID 37478173, 2023). "The inherent cross-sectional design precludes establishing causal relationships, while the small sample size may have affected the detection of the mediation role of TRPA1 in the relationship between olfactory function and cognitive impairment." (PMID 38915349, 2024). "Odds ratios for serum TRPA1 between participants with normal cognition and cognitive impairment." (PMID 38915349, 2024). "Together, TRPA1 stimulation ameliorates BCAS-induced outcomes, such as cognitive impairment and white matter injury." (PMID 37478173, 2023). "Consistent with cognitive impairment, the myelin density was significantly decreased in BCAS-operated TRPA1-KO mice compared with sham-operated TRPA1-KO mice." (PMID 37478173, 2023). "Together, our results indicate that TRPA1 deficiency accelerates CCH-induced VCI and white matter injury from early-stage CCH, on day 14, when BCAS-operated WT mice do not show cognitive impairment and marked white matter injury." (PMID 37478173, 2023). "During early-stage CCH, cognitive impairment and white matter injury were induced by BCAS in TRPA1-knockout but not wild-type mice." (PMID 37478173, 2023).